MIR135B (microRNA 135b)
Synonyms: hsa-mir-135b; MIRN135B; mir-135b
Gene: MicroRNA gene on chromosome 1 (205,448,302 to 205,448,398, reverse strand). Ensembl gene ENSG00000199059.
Gene Ontology:
Biological process: miRNA-mediated post-transcriptional gene silencing
Cellular component: RISC complex
Homologues: Orthologues: chimpanzee ptr-mir-135b (100% identical), guinea pig MIR135B (96% identical), rat Mir135b (96% identical), macaque MIR135B (95% identical), pig MIR135B (89% identical), dog MIR135B (86% identical), tropical clawed frog xtr-mir-135-2 (67% identical), zebrafish mir135c-2 (62% identical), zebrafish mir135c-1 (60% identical). Paralogues in human: MIR135A1 (62% identical), MIR135A2 (62% identical).
Diseases named in the same sentence as MIR135B in open-access papers:
MIR135B is named in the same sentence as 4 diseases in open-access papers, as found by Europe PMC text mining. Sharing a sentence is not in itself a finding about the gene and the disease. The quoted sentences say what the papers report.
glioma (1 paper, 2013). A benign or malignant brain and spinal cord tumor that arises from glial cells (astrocytes, oligodendrocytes, ependymal cells). "MIR135B, MIR182 and MIR183 are overexpressed in a wide range of other cancer types such as bladder, colon, prostate cancer and glioma." (PMID 24053169, 2013).
MIR135B also shares sentences with these, for which no sentence is quoted: cancer (1 paper); pancreatic adenocarcinoma (1); prostate carcinoma (1).